TNF (tumor necrosis factor)
Diseases named in the same sentence as TNF in open-access papers (continued):
Sharing a sentence is not in itself a finding about the gene and the disease.
Stroke (continued). "Our research also revealed that in the classic tMCAO stroke model, the levels of TNF-α and IL-1β, two of the five core target genes, increased significantly." (PMID 41471340, 2025). "Our previous study demonstrated that HDAC1 inhibition at 24 h after stroke exacerbated gliosis and elevated IL-1β and TNF-α, underscoring its importance in the acute phase." (PMID 41388741, 2025). "Gene expression profiling revealed an upregulation of proinflammatory cytokines (TNF-α, IL-1β, IL-6) and the anti-inflammatory cytokine IL-10, particularly during the first three days post-stroke." (PMID 41373607, 2025). "Proinflammatory intracellular signaling cascades and transcription factors, for example, NF-κB, ROS, MMPs, and the release of proinflammatory cytokines, especially IL-1β, IL-6, and TNF-α, are associated with BBB dysfunction after stroke." (PMID 40740844, 2025). "Pro-inflammatory factors secreted by neutrophils, such as TNF-α and IL-6, promote the expression of MMP-9, which exacerbates endothelial damage in cerebral vessels following stroke and increases the risk of hemorrhagic complications." (PMID 40697574, 2025). "Receiver operating characteristic (ROC) analysis was performed to assess the diagnostic accuracy of IL-6, TNF-alpha, and NIHSS at admission in predicting stroke outcomes." (PMID 39859987, 2025). "In the early phase of stroke, IL-6 is induced by IL-1β and TNF-α and amplifies the inflammatory cascade." (PMID 40869247, 2025). "In our previous study we showed that salivary TNF-α distinguished stroke patients from healthy individuals with high specificity and sensitivity." (PMID 40221607, 2025). "Critically, the initiation of anti-TNF therapy resulted in complete stroke cessation, underscoring its importance in disease management." (PMID 41413740, 2025). "For example, increased IL-6 and TNF-α levels during the acute phase correlate with larger infarct volumes and higher disability scores at three months post-stroke." (PMID 40869247, 2025). "Stroke induces the release of pro-inflammatory cytokines, such as interleukin-6 (IL-6), interleukin-1β (IL-1β), tumor necrosis factor-α (TNF-α), and interleukin-18 (IL-18), while reducing anti-inflammatory cytokines like IL-10 and IL-13." (PMID 40529498, 2025). "Stroke can trigger the release of various immune mediators, including IL-1β, TNF-α, calcitonin gene-related peptides, neuropeptides, and vasoactive intestinal peptides." (PMID 40098935, 2025). "In our previous study, we evaluated the diagnostic potential of unstimulated and stimulated saliva in assessing TNF-α, IL-6 and IL-10 in stroke patients." (PMID 40520895, 2025). "In stroke, IL-10 modulates the immune response by inhibiting the synthesis of pro-inflammatory cytokines (e.g., IL-1β, IL-6, TNF-α), suppressing antigen presentation, and downregulating adhesion molecules on endothelial cells." (PMID 40869247, 2025). "In our previous studies, we demonstrated the diagnostic potential of salivary tumor necrosis factor α (TNF-α), interleukin 6 (IL-6), interleukin 10 (IL-10) and xanthine oxidase (XO) in the differential diagnosis of stroke patients." (PMID 40520895, 2025). "Typically, after a stroke, inflammatory factors such as TNF-α and IL-6 transform resident microglia into inflammatory microglia, which in turn release similar inflammatory factors." (PMID 40109397, 2025). "The enhanced expression of HSP60 on day 7 in pigs corresponded with HIF1α, NF-κβ and TNFα allowing for the presumption of a role for HSP60 in maintaining or triggering the inflammatory response after stroke." (PMID 40332314, 2025). "As we move forward, the exploration of novel anti-inflammatory treatments targeting IL-6 and TNF-alpha presents promising avenues for improving post-stroke recovery and reducing long-term disability." (PMID 39859987, 2025).
Stroke (continued). "Various triggers, such as febrile seizures, stroke, infection, or trauma, can initiate an inflammatory cascade that releases pro‐inflammatory cytokines, such as IL‐1β and TNF‐α, and danger signals, such as HMGB1." (PMID 38361811, 2024). "For cytokines assayed in whole brain homogenates, both Kdm6afl/fl and Kdm5cfl/fl mice had significantly higher levels of TNF-α than either fl/y or CKO mice after stroke." (PMID 39399684, 2024). "Cytokines released during stroke, such as TNF-α, IL-1β, and IL-6, further activate the inflammatory response and induce cell death." (PMID 38742047, 2024). "Research showed that H. pylori infection induced the production of pro-inflammatory cytokines, including IL-1β, IL-6, and TNF-α in gastric epithelial cells, contributing to gastric inflammation and potentially to systemic conditions such as stroke." (PMID 39202269, 2024). "Several observational studies have reported associations of inflammatory biomarkers such as CRP, TNF-α, and Interleukin-6 (IL-6) with PSD/depressive symptoms after stroke." (PMID 37848651, 2024). "NPAS4 deficiency in mice results in an increase in activated microglia and astrocytes as well as increased protein levels of IL-6 and TNF-α after stroke." (PMID 37938766, 2024). "Elevated levels of cytokines, including IL-1β, TNF-α, and IL-6, in the bloodstream of stroke patients imply a higher likelihood of deterioration of their condition." (PMID 38742047, 2024). "Inflammatory mediators produced by microglia, such as pro-inflammatory cytokines (TNF-α, IL-1β, and IL-6), significantly promote neuroinflammation, thereby mediating stroke." (PMID 38468280, 2024). "For example, in conditions like multiple sclerosis or stroke, the peripheral levels of cytokines such as interleukin-6 (IL-6), tumor necrosis factor-alpha (TNF-α), and interleukin-1 beta (IL-1β) have been found to be elevated." (PMID 38285083, 2024). "Experimental studies in stroke models have shown that probiotics produce an anti-inflammatory and antioxidant response by suppressing TNF-α and free radical production through the modulation of TLR activation in the gut." (PMID 39767686, 2024). "Increased levels of TNF-α from activated microglia have been demonstrated to persist for a minimum of 15 months following stroke in the human brain." (PMID 40789569, 2024). "We then evaluated the levels of TNF-α, one of the main cytokines in the inflammatory response observed after stroke." (PMID 38255316, 2024). "A clinical study indicated that post-stroke patients have elevated levels of TNF-α, and an in vitro study determined that TNF-α significantly impairs the function and integrity of the BBB." (PMID 38247804, 2024). "TMAO manifests opposite effects given that it can directly activate platelets, augmenting the likelihood of thrombosis and stroke as well as increasing the expression of pro-inflammatory cytokines, such as TNF-α, IL-6, and C reactive protein." (PMID 38787240, 2024). "Reducing serum inflammatory factors (such as high-sensitivity C-reactive protein, tumor necrosis factor-α, interleukin-6) in patients with stroke." (PMID 39211435, 2024). "A recent study in patients with ischemic stroke reported that BMI was inversely associated with IL-6 levels after major stroke, while eotaxin, IFN-β, IFN-γ, and TNF-α were upregulated when BMI increased." (PMID 38206990, 2024). "CD11bhigh B cells can increase the microglia phenotype via regulatory cytokines (TNF-α) in immune-dysregulated aged stroke mice." (PMID 37728582, 2024). "Lower serum GPR37 levels and higher levels of inflammatory markers such as S100β, neuron-specific enolase (NSE), IL-1β, and TNF-α are observed in stroke patients compared to healthy controls." (PMID 39633709, 2024). "Research shows that activation of monocytes after stroke increases NF-κB signaling and TNF-α production, which correlates with worse stroke outcome." (PMID 39000490, 2024).
Stroke (continued). "Stroke also activates apoptosis in injured brain cells through the extrinsic pathway, which occurs through signaling between tumor necrosis factor (TNF), Fas, and Trail cell surface death receptors." (PMID 39000490, 2024). "Lower concentrations of IL-4, IL-6, and TNF-α were negatively correlated with stroke patients suffering from hyperhomocysteinemia (IL-4: P = 0.015, χ2 = 6.040; IL-6: P = 0.015, χ2 = 6.038; TNF-α: P = 0.016, χ2 = 6.243)." (PMID 38287458, 2024). "Gene floxed females showed more robust expression of CD68 in microglia, elevated brain and plasma levels of IL-1β or TNF-α, after stroke." (PMID 39399684, 2024). "Severely affected stroke patients measured via the NIHSS had higher TNF-alpha levels compared to less severely affected patients (NIHSS>30; 225.32 pg/mL, SD: 163.6 vs. NIHSS ≤30 52.744 pg/mL, SD: 26.86, p = 0.0001)." (PMID 39091977, 2024). "The present results show that HGS stroke patients have significantly higher circulating levels of IL-1β, whereas IL-6 levels only showed a trend to increase and TNF-α levels were unchanged." (PMID 36536168, 2024). "TNFα levels are increased both during ageing and in stroke and TNFα treatment increased both bond number and affinity between early outgrowth EPCs and rat cardiac microvascular endothelial cells." (PMID 39529098, 2024). "Investigations into cytokine levels in stroke models with exercise intervention consistently report reductions in pro-inflammatory cytokines, such as tumor necrosis factor alpha (TNF-α), IL-1β, and interleukin 6 (IL-6)." (PMID 38911597, 2024). "Specifically, experimental studies have described the role of TNF-α in gut bacterial dissemination and microbiota alterations after stroke." (PMID 39767686, 2024). "Tumor necrosis factor-α (TNFα) is a specific pro-inflammatory cytokine, which is highly expressed in stroke." (PMID 39021802, 2024). "For example, the activation of the IL-17 and TNF signaling pathways points to the possibility of targeting these pathways to mitigate stroke-related inflammation and reduce neuronal damage." (PMID 39697434, 2024). "The exacerbation of TNFα production by perivascular cells plays a key role in neuroinflammation and vascular leakage after stroke." (PMID 39187765, 2024). "In stroke patients, markers like interleukin-6 (IL-6), tumor necrosis factor (TNF), and neutrophil counts were markedly increased." (PMID 38699426, 2024). "The upregulation of TNF-α and IL-1 after a stroke activates phospholipases and sphingomyelinase, which results in the loss of PC and SM but the elevation of AA and Cer." (PMID 38535293, 2024). "AEVs derived from reactive astrocytes with anti-inflammatory properties possess CD63 and CD9 tetraspanins and miR-146a-5p, which regulate glial scars by suppressing NF-κB and TNF-α, which permit axonal outgrowth, thereby improving stroke recovery." (PMID 37676390, 2024). "Elevated TNF-α levels in the colon of older mice promoted the translocation of bacteria to the lungs following stroke." (PMID 39767686, 2024). "In an independent experimental group, IL-6 and TNF-α, used as markers of inflammation after stroke, were analyzed in ischemic mice before and after the treatment with the vehicle and CSM@rtPA." (PMID 38166940, 2024). "Following a stroke, activated microglia secrete a combination of IL-1α, TNF-α and C1q, prompting astrocytes to adopt a neurotoxic phenotype, which contributes to the complexity of the neuroinflammatory response." (PMID 38377025, 2024). "Therefore, future investigations are crucial in identifying whether neuroinflammatory agents, such as TNF-a, IL-6, or IL-1b, contribute to the association of stroke risk with RA and whether these agents are similarly influential in other inflammatory diseases, such as ankylosing spondylitis." (PMID 38294723, 2024). "Serum SIRT2 levels were also positively correlated with NIH Stroke Score, tumor necrosis factor-α, IL-6 and IL-17." (PMID 39001884, 2024).
Stroke (continued). "In this study were analysed glutamate, IL-1β, IL-6, IL-10 and TNF-α according to the time of stroke." (PMID 36835156, 2023). "Inhibit stroke-induced inflammatory response by decreasing the number of Ly-6Chigh MMs subset and reducing expression of TNFα, IL-6, IL-1β and MCP-1." (PMID 37342335, 2023). "Consistently, the protein level of TNF-α was also up-regulated in Tmem119-CreERT2; Nr4a1fl/fl mice at 24 h after stroke." (PMID 37486903, 2023). "Stress in stroke stimulates peripheral immune cells to secrete pro-inflammatory cytokines, TNF-α, IL-1β and IL-6, which can cross the BBB and further activate microglia and astrocytes in the CNS to secrete more pro-inflammatory cytokines." (PMID 37199575, 2023). "The plasma TNF-alpha levels were shown to be significantly increased in stroke cases compared to healthy controls, and that suppression of TNF-alpha was suggested to be a therapeutic strategy for stroke." (PMID 37240845, 2023). "Several studies have reported that pro-inflammatory cytokines (i.e., interleukin-1, interleukin-6 and TNFα (tumor necrosis factor alpha)) play a major role in the development of inflammation after stroke." (PMID 37298395, 2023). "This study also found that IGF-1 treatment inhibited levels of inflammatory cytokines such as TNF-α, IL-1β, and IL-6 at 4 h after stroke, while only IL-6 and IL-13 continued to be inhibited at 24 h after stroke, as did chemokines GRO-KC and CCL2." (PMID 37638322, 2023). "The roles of VWF, GSTs and TNF-alpha gene variations in the induction of stroke are still uncertain and require further examination." (PMID 37240845, 2023). "Neuroinflammation is an important pathogenic factor in cerebral ischemia–reperfusion, and it has been reported that stroke activates the expression of pro-inflammatory cytokines, such as TNF and IL-1β." (PMID 37630972, 2023). "Etanercept, a TNF alpha inhibitor, has been shown to improve inflammation that leads to post-stroke pain." (PMID 37065345, 2023). "In accordance with its potential dual role, TNF-α inhibition in experimental models of ischemic stroke showed both beneficial and detrimental effects on stroke size and neurological deficit." (PMID 36745280, 2023). "The main specific targets proposed for stroke therapies are the cytokines TNF-α, IL-1β, and IL-6, and the adhesion molecule ICAM-1, which will be discussed in this section." (PMID 37762627, 2023). "The M1 subtype can secrete pro-inflammatory factors, including TNF-α and IL-1β, aggravating neuroinflammation post-stroke." (PMID 37464832, 2023). "Further research is required to understand the specific role and mechanism that TNF alpha plays in brain injury due to stroke and to minimize the side effects of anti-TNF alpha therapy." (PMID 37065345, 2023). "Types of TNF alpha include soluble (sol) and transmembrane (tm) types, which can contribute to the complex inflammatory response seen during the stroke." (PMID 37065345, 2023). "Elevated levels of TNF alpha expression have been observed in the cerebrospinal fluid (CSF) of patients with various degenerative diseases such as AD, PD, MS, and stroke." (PMID 38069032, 2023). "In a rat stroke study on MnTnHex-2-PyP5+, we have demonstrated the inhibition of NF-κB and subsequent downregulation of NF-κB-controlled pro-inflammatory cytokines, TNF-α and IL-6." (PMID 37891940, 2023). "Production of other pro-inflammatory cytokines (TNF-alpha, IL-6) is significantly increased at 24 h of stroke which also initiates the synthesis of anti-inflammatory cytokines to protect the tissue itself (TGF-beta, IL-10)." (PMID 37822799, 2023). "The mRNA expression of proinflammatory cytokines, including TNF-α and IL-6, was significantly elevated at 5 d after stroke in Sig-1R-/- mice." (PMID 36632219, 2023). "Etanercept is a potent anti-TNF (tumour necrosis factor) fusion protein and TNF inhibitor and was of interest for treating neuroinflammatory disorders such as stroke and Alzheimer’s disease." (PMID 37242623, 2023).
Stroke (continued). "During the early stages of stroke, IL-1 mediates harmful inflammatory processes, such as the upregulation of IL-6, TNF-α, Matrix metallopeptidase 9 (MMP-9), and chemokines in astrocytes, inhibition of neurogenesis." (PMID 36793730, 2023). "Given that both HSP70 and TNF-α transcripts are targeted by HuR, we also determined the level of HuR protein in the peri-stroke tissue in order to examine the direct effect of minocycline on this RNA-stabilizing protein." (PMID 37298395, 2023). "Serum TNF-α levels were higher in patients with symptomatic focal epilepsy (SFE) associated with traumatic brain injury, stroke, or other cerebrovascular disorders compared to patients with SFE related to other causes." (PMID 38069144, 2023). "Consistent with previous studies, the dramatic increase in stroke-induced inflammatory cytokines TNF-α, IL-1β, and IL-6 was suppressed after treatment with NSC-EV." (PMID 37691119, 2023). "Overexpression of KLF2 in mice led to smaller stroke volumes and protected against TNF-α-mediated BBB dysfunction." (PMID 36942087, 2023). "We used Western blotting to assess the amount of TNFα protein in the peri-stroke tissue, which supported the immunohistochemistry results." (PMID 37298395, 2023). "The results of this study indicate that the levels of plasma iFABP, IL-6, and TNF-α in the PSD group are significantly higher compared to that in the stroke group." (PMID 38084247, 2023). "Analyze various randomized clinical trials that study perispinal etanercept’s effect on post-stroke pain and the role of TNF alpha in the development of post-stroke pain." (PMID 37065345, 2023). "In conclusion, this randomized, controlled trial demonstrates that IL-17A and TNF-α play an inflammatory role in the acute and subacute stages of stroke and aggravate brain injury, while VEGF-A exerts a neuroprotective effect." (PMID 37287803, 2023). "In almost all patients who received treatment with biologic TNF inhibitors, fever episodes, vasculopathy, and stroke prevention were successfully managed." (PMID 36606112, 2023). "For example, TNF-α was elevated two- to three-fold in severe and mild-to-moderate stroke, whereas IL-6 had a nearly 30-fold increase in severe stroke and only a 10-fold increase in mild-to-moderate stroke." (PMID 37446092, 2023). "Serum IDO1 levels were significantly higher in stroke patients carrying the TNF-α rs361525 G/G genotype than in those carrying the G/A genotype (Z = -2.451, p = 0.014), indicating that TNF-α rs361525 polymorphism was associated with serum IDO1 levels." (PMID 36911716, 2023). "Higher levels of IL-10 and tumor necrosis factor (TNF) were found in patients with AF, compared with controls, and the latter was also suggested as a predictive marker of stroke in patients with NVAF." (PMID 36834735, 2023). "Baek and colleagues explored the role of inflammation in stroke pathophysiology by measuring mRNA expression levels of interleukin (IL)-1β, IL-6, IL-8, IL-18, tumor necrosis factor (TNF)-α, matrix metallo-proteinase (MMP)-2, and MMP-9 in retrieved thrombi." (PMID 36834829, 2023). "12/15-LOX inhibition significantly decreased IL-1beta, IL-6, and TNF-alpha protein levels at 24-h of stroke." (PMID 37822799, 2023). "The use of TNF alpha as a main biomarker of stroke development or prognosis is a promising area of research to explore." (PMID 37065345, 2023). "Three major pro-inflammatory cytokines—IL-1β, TNF-α, and IL-6—both mediate and aggravate the inflammatory response following stroke." (PMID 38102677, 2023). "With intraperitoneal administration of EA 24 h pre-stroke, EA reduced the serum protein expressions of proinflammatory cytokines iNOS, IL-1, IL-6, and TNF-α in the cerebral global ischaemic stroke animal model." (PMID 36675019, 2023). "Stroke patients with the TNF-α rs361525 G/G genotype had higher serum IDO1 levels compared to those with the G/A genotype (Z = -2.451, p = 0.014)." (PMID 36911716, 2023).